GPHB5 (glycoprotein hormone subunit beta 5)
Description:
Functions as a heterodimeric glycoprotein hormone with GPHA2 able to bind and activate the thyroid-stimulating hormone receptor (TSHR), leading to increased cAMP production. Plays a central role in controlling thyroid cell metabolism.
Synonyms: GPB5; ZLUT1; B5
Tractability: Antibody: its Gene Ontology location is reachable by antibodies, with high confidence; UniProt places it where antibodies can reach, with medium confidence; UniProt predicts a signal peptide or a membrane-spanning region.
Gene: Protein-coding gene on chromosome 14 (63,312,835 to 63,318,935, reverse strand). Ensembl gene ENSG00000179600.
Subcellular location: Secreted
Pathways (Reactome):
Signal Transduction: G alpha (s) signalling events; Hormone ligand-binding receptors
Gene Ontology:
Molecular function: protein binding; protein heterodimerization activity; thyrotropin-releasing hormone receptor binding; hormone activity
Biological process: adenylate cyclase-activating G protein-coupled receptor signaling pathway; G protein-coupled receptor signaling pathway
Cellular component: extracellular region
Genetic constraint (gnomAD): Loss-of-function variants: 7 observed, 9.78 expected, observed/expected ratio (o/e) 0.72, 90% interval 0.41 to 1.34. That is too few expected variants to judge how well the gene tolerates losing a copy. Missense variants: 161 observed, 168.96 expected, observed/expected ratio (o/e) 0.95, 90% interval 0.84 to 1.09. Synonymous variants: 68 observed, 68.76 expected, observed/expected ratio (o/e) 0.99, 90% interval 0.81 to 1.21.
Homologues: Orthologues: chimpanzee GPHB5 (100% identical), macaque GPHB5 (96% identical), dog GPHB5 (92% identical), pig GPHB5 (92% identical), rabbit GPHB5 (92% identical), guinea pig GPHB5 (87% identical), mouse Gphb5 (87% identical), rat Gphb5 (86% identical), tropical clawed frog gphb5 (71% identical), zebrafish gphb5 (65% identical), Drosophila melanogaster Gpb5 (28% identical). Paralogues in human: CGB3 (28% identical), CGB5 (28% identical), CGB7 (28% identical), CGB8 (28% identical), FSHB (28% identical), LHB (28% identical), CGB1 (26% identical), CGB2 (26% identical), TSHB (25% identical).
Diseases named in the same sentence as GPHB5 in open-access papers:
GPHB5 is named in the same sentence as 14 diseases in open-access papers, as found by Europe PMC text mining. Sharing a sentence is not in itself a finding about the gene and the disease. The quoted sentences say what the papers report.
Obesity (5 papers, 2015 to 2026). Accumulation of substantial excess body fat. "The results show that the level of circulating GPHB5 levels was significantly increased in MetS subjects, which was significantly related to MetS components, such as obesity, hyperglycemia, hyperlipidemia and blood pressure." (PMID 35757403, 2022). "In conclusion, circulating GPHB5 levels were elevated in PCOS and IR populations and associated with glucose and lipid metabolism disorders, obesity and IR." (PMID 36568071, 2022). "Circulating GPHB5 levels were significantly correlated with obesity, glucose and lipid metabolism, and IR." (PMID 35757403, 2022). "Genetic ablation of GPHB5 in men, but not women, reduced the browning of white adipose tissue, diminished energy expenditure, and caused severe obesity." (PMID 41632528, 2026). "Knockout of AR led not only to development of obesity but also reduction of GPHB5 expression." (PMID 41632528, 2026).
Hyperglycemia (2 papers, 2022). An increased concentration of glucose in the blood. "We found that hyperglycemia and hyperinsulinemia caused by glucose challenge did not lead to changes in circulating GPHB5 levels." (PMID 36568071, 2022). "To exclude the interference of hyperglycemia, we performed an EHC study, the gold standard for evaluating insulin sensitivity, and measured circulating GPHB5 levels in women with IR and PCOS and normal individuals." (PMID 36568071, 2022).
Hyperinsulinemia (2 papers, 2022). An increased concentration of insulin in the blood. "Lipid-infusion-induced serum FFA increase and EHC hyperinsulinemia did not cause a significant increase in circulating GPHB5 concentration." (PMID 35757403, 2022). "However, whether GPHB5 in T2DM is affected by IR-induced long-term hyperinsulinemia and high FFA levels remains unclear, and further research is needed." (PMID 35757403, 2022). "However, short-term hyperinsulinemia did not lead to changes in circulating GPHB5 levels." (PMID 36568071, 2022).
Insulin resistance (2 papers, 2022 to 2025). Increased resistance towards insulin, that is, diminished effectiveness of insulin in reducing blood glucose levels. "Collectively, these findings suggest that GPHB5 is associated with impaired glucose and lipid metabolism and insulin resistance, potentially functioning as a negative regulator of metabolic homeostasis." (PMID 41373675, 2025). "GPHB5 levels showed a positive correlation with body mass index (BMI) and Homeostatic Model Assessment of Insulin Resistance (HOMA-IR), and a negative correlation with markers of insulin sensitivity, including the Euglycemic Hyperinsulinemic Clamp (EHC), M-values, and adiponectin levels." (PMID 41373675, 2025).
metabolic syndrome (2 papers, 2022 to 2025). A cluster of metabolic risk factors for CARDIOVASCULAR DISEASES and TYPE 2 DIABETES MELLITUS. "In young women diagnosed with metabolic syndrome (MetS), circulating GPHB5 levels have been proposed as a potential biomarker, as they were found to be significantly elevated compared to healthy controls." (PMID 41373675, 2025). "Its expression appears to be influenced by the liver’s metabolic state in MetS patients, reinforcing the hypothesis that GPHB5 may play a critical role in the pathophysiology of metabolic syndrome." (PMID 41373675, 2025).
Graves disease (1 paper, 2022). Graves' disease is an autoimmune disorder that leads to overactivity of the thyroid gland (hyperthyroidism).It is caused by an abnormal immune system response that causes the thyroid gland to produce too much thyroid hormones. "In addition, an animal study showed that GPHB5 transgenic mice showed a phenotype of Grave’s disease in humans since GPHB5 served as an alternate ligand for the TSHR." (PMID 35757403, 2022).
metabolic disease (2 papers, 2022). A congenital disorder (due to inherited enzyme abnormality) or acquired (due to failure of a metabolically important organ) disorder resulting from an abnormal metabolic process. "After 6 months of treatment, with weight loss and the improvement of metabolic disorder and IR, the levels of circulating Adipoq increased significantly, while the level of GPHB5 decreased significantly." (PMID 36568071, 2022). "In our study, the strong association of circulating GPHB5 with IR and metabolic disorders is confirmed." (PMID 36568071, 2022). "Bioinformatics analysis shows that GPHB5 is associated with metabolic disorders and PCOS." (PMID 36568071, 2022). "Bioinformatics analysis was performed to understand the relationship between GPHB5 and metabolic disorders." (PMID 36568071, 2022). "Especially in the occurrence and development of metabolic diseases, the role of GPHB5 is poorly understood." (PMID 35757403, 2022). "In summary, the present study explores the relationship between GPHB5 and metabolic diseases for the first time." (PMID 35757403, 2022). "In the current study, we find that GPHB5 is related to metabolic disorders, IR and PCOS through internet data analysis." (PMID 36568071, 2022). "In this study, we first discovered the connection between GPHB5 and metabolic disorders through bioinformatics analysis." (PMID 35757403, 2022). "Our aim in this study was to investigate the relationship between circulating GPHB5 and metabolic disorders in humans." (PMID 36568071, 2022). "However, unlike previous studies, our results show that the increase in GPHB5 may promote IR and metabolic disorders." (PMID 36568071, 2022). "However, the association of GPHB5 with IR and metabolic disorders remains unknown, and there is a lack of research in humans." (PMID 36568071, 2022). "Therefore, GPHB5 may be a biomarker related to all metabolic disorders." (PMID 35757403, 2022). "However, the relationship between GPHB5 and metabolic diseases remains unknown." (PMID 35757403, 2022). "But, the relationship between GPHB5 and metabolic diseases as well as its role has not been reported in humans." (PMID 36568071, 2022). "In addition, correlation analysis showed that the increased circulating GPHB5 level was positively correlated with BMI and HOMA-IR but negatively correlated with the M-value of EHC and adiponectin, suggesting that the increase in GPHB5 levels may promote metabolic disorder and IR." (PMID 36568071, 2022).
tumor (2 papers, 2016 to 2022). "It has been found that GPHB5 and GPHA2 can form a heterodimer (GPHB5/GPHA2) and are secreted into the blood to participate in reproduction, tumor cell proliferation, skeletal development, and immune and inflammatory regulation." (PMID 36568071, 2022).
GPHB5 also shares sentences with these, for which no sentence is quoted: polycystic ovary syndrome (2 papers); Chagas disease (1); diabetic cardiomyopathy (1); hyperlipidemia (1); infection (1); lipid metabolism disorders (1).